RAD21 (RAD21 cohesin complex component)
Diseases named in the same sentence as RAD21 in open-access papers (continued):
Sharing a sentence is not in itself a finding about the gene and the disease.
breast carcinoma (continued). "His father, who transmitted RAD21 p.P298S to his son, had died from breast cancer at the age of 41." (PMID 35563565, 2022). "In breast cancer, RAD21 was identified as a gene related to tamoxifen treatment response." (PMID 35860572, 2022). "Furthermore, patients with breast cancer who harbor RAD21 alterations had poor median overall survival and trended towards higher levels of Ki-67 staining." (PMID 35227290, 2022). "In conclusion, RAD21 is a potential predictive and prognostic biomarker in familial breast cancers." (PMID 35740618, 2022). "In breast cancer cells, RAD21 is required for expression of a subset of estrogen induced genes." (PMID 34202641, 2021). "High levels of nuclear RAD21 staining correlate with poor disease-specific survival of colorectal cancer patients with KRAS mutations and with early relapse in patients with high-grade luminal, basal, or HER2 breast cancers." (PMID 28434945, 2017). "For example, knockdown of Rad21 significantly inhibited the proliferation of breast cancer MCF-7 cells and increased their sensitivity to respond to chemotherapeutic the agents etoposide and bleomycin, suggesting that Rad21 is associated with proliferation and chemoresistance in breast cancer cells." (PMID 28831167, 2017). "Another recent study identified RAD21 as a driver gene within the corresponding cytoband amplification regulating the proliferation and survival of breast cancer cells, and suggested it as a potential target whose inhibition can lead to apoptosis in tumour cells." (PMID 27341628, 2016). "Additionally in breast cancer, gains at the cohesin gene chromosomal loci seem to occur more frequently at the RAD21 loci and down-regulation of RAD21 in human breast cancer cell lines was shown to increase its sensitivity to cancer chemotherapeutic agents." (PMID 23717600, 2013). "We therefore performed the first analysis of RAD21 in a cohort of fully characterized familial breast cancers and investigated potential mechanisms that may mediate RAD21 levels, including DNA copy number and reduced expression of targeting microRNA." (PMID 22537934, 2012). "A study showing that RAD21 depletion prevents estrogen-induced G0/G1-S transition in breast cancer cells is consistent with regulation of MYC by cohesin, since a large proportion of genes involved in estrogen-stimulated cell cycle progression are downstream of MYC." (PMID 23145106, 2012). "In addition, clinical breast cancer samples have higher RAD21 mRNA levels than normal breast tissue, and these higher levels are associated with poor prognosis." (PMID 23145106, 2012). "To determine whether cohesin is required for estradiol-mediated activation of MYC in other ER-positive cell lines, we used siRNA to deplete RAD21 in T47D breast cancer cells." (PMID 23145106, 2012). "Potential use of RAD21 as a predictive and prognostic marker in familial breast cancers is hence feasible and may therefore take into account the patient's BRCA1/2 mutation status." (PMID 22537934, 2012). "Although RAD21 overexpression correlates with early relapse and treatment resistance in sporadic cancers, it is unclear whether familial breast cancers behave in a similar manner." (PMID 22537934, 2012). "To determine whether cohesin regulates MYC in human breast cancer cell lines we transfected MCF7 cells with siRNA targeting the RAD21 subunit of cohesin." (PMID 23145106, 2012). "Based on known RAD21 functions, the adverse outcome in breast cancer patients with RAD21 expression could be due to an elevated level of homologous recombination (HR) repair activity as a result of RAD21 overexpression." (PMID 21255398, 2011). "Since our analysis showed that RAD21 expression strongly correlates with TOP2A expression in a number of breast cancer cell lines, we assessed the sensitivity of RAD21 knockdown clones to etoposide, a topoisomerase II inhibitor and commonly used anti-cancer drug." (PMID 21255398, 2011).
breast carcinoma (continued). "Our findings in breast cancer with the RAD21 cohesin may also generalize to some other epithelial cancer types: consistent with our data, RAD21 at chromosomal locus 8q24 is also commonly amplified in advanced androgen-resistant prostate cancer." (PMID 21255398, 2011). "Immunohistochemical evaluation of RAD21 protein on breast cancer specimens could be routinely incorporated into standard pathology reporting to estimate levels of RAD21 that might determine drug response of certain drug regimens." (PMID 21255398, 2011). "RAD21 may be a novel marker of poor prognosis, a predictive factor for systemic therapy outcomes and a new target for breast cancer therapy." (PMID 21255398, 2011). "Inhuman breast cancer cells, expression level of RAD21 is higher than normalcells." (PMID 18551189, 2008). "Inhibition of RAD21 lows the survival rate of breast cancer cells andinduces apoptotic cell death." (PMID 18551189, 2008). "Moreover, RAD21 depletion inhibited proliferation and sensitized breast cancer cell lines to Etoposide and Bleomycin, suggesting that targeting cohesin may be an effective treatment either alone or in combination with chemotherapy." (PMID 23145106, 2012). "Further overlaps with breast cancer cell dependencies revealed SUPT6H and RAD21, along with their respective protein systems, HOST:37 and HOST:861, as potential biomarkers." (PMID 39838298, 2025). "Published data reported that RAD21 mRNA amplification correlates with gene copy number in grade 3 luminal, basal and HER2 subtypes of breast cancer." (PMID 37474724, 2023). "Enhanced RAD21 expression was correlated with early relapse and chemotherapy resistance in high-grade luminal, basal, and HER2 breast cancers." (PMID 35860572, 2022). "In the literature, RAD21 (Gene Entrez ID 5885) was validated as a luminal, basal, and ERBB2 breast cancer gene marker." (PMID 34573857, 2021). "We next sorted the RNASeq data of primary breast cancer patients based on RESTlow and RESThigh groups with 300 patients for each group and examined the expression patterns of TBP, CEBPB, REST, CTCF, RAD21 and SMC3 in addition to unsorted patient dataset." (PMID 30335837, 2018). "While RAD21, BIRC5 and AURKA have already been recognised as important players in luminal breast cancers progression process, the remaining genes represent novel biomarkers and targets to explore." (PMID 27341628, 2016). "In another study, siRNA-mediated knockdown of the iPAC gene RAD21 was found to decrease cell growth and enhance cytotoxicity in MCF7 and T47D breast cancer cell lines." (PMID 23382830, 2013). "We found that siRNA-targeted depletion of a cohesin subunit, RAD21, decreased MYC expression in ER-positive (MCF7 and T47D) and ER-negative (MDA-MB-231) breast cancer cell lines." (PMID 23145106, 2012). "In summary, expression of RAD21 in a significant subset of breast cancers confers poor prognosis in high grade luminal, basal and HER2 breast cancers, and resistance to chemotherapy in breast cancer." (PMID 21255398, 2011). "Consistent with this proposition, we noted that both topoisomerase II and the RAD21 loading protein NIPBL, showed strong coordinately regulated expression with RAD21 in breast cancer cell lines." (PMID 21255398, 2011). "RAD21 expression confers poor prognosis and resistance to chemotherapy in high grade luminal, basal and HER2 breast cancers." (PMID 21255398, 2011). "RAD21, however, is the most frequently amplified cohesin in non-small-cell lung cancer, breast cancer cells, cervical cancer, ovarian cancer, oral cancer and prostate cancer." (PMID 41370327, 2025). "The amplification of PTK2, MYC, NBN, and RAD21 found prognostic biomarkers independent of breast cancer subtype." (PMID 35494043, 2022). "Additionally, high Rad21 expression in patients with high‐grade luminal, basal, and human epidermal growth factor receptor 2 (HER2)‐positive breast cancers shortens the overall survival of patients and decreases chemosensitivity." (PMID 29797792, 2018).
breast carcinoma (continued). "In addition, our data show that even a partial reduction of RAD21 completely blocks the transcriptional response of MYC to estradiol, or other growth regulatory pathways, in breast cancer cell lines." (PMID 23145106, 2012). "Neither of these findings appears to be reflected by our clinical cohorts, as Rad21 expression did not correlate with survival in either sporadic (P = 0.231) or familial (P = 0.881) breast cancers treated with hormone therapy." (PMID 22537934, 2012). "Our findings in a cohort of familial breast cancers recapitulated our previous findings in sporadic breast cancers, with enhanced expression of RAD21 occurring in a subset of tumors regardless of grade, size, or intrinsic subtype." (PMID 22537934, 2012). "Similar to our previous findings in sporadic breast cancers, high RAD21 expression correlated with poorer relapse-free survival (P = 0.008) and breast cancer-specific survival for grade 3 familial breast cancers (P = 0.009), but not for grade 1 and 2 cancers (P = 0.065 and 0.090, respectively)." (PMID 22537934, 2012). "Although these reports support the notion that the abnormal activity of RAD21 may be an important feature of human breast cancer, there are no data available from clinical breast cancer samples." (PMID 21255398, 2011). "To test the functional significance of our cancer therapy results that RAD21 expression affects sensitivity to chemotherapeutic drug response, we used a small hairpin shRNA-mediated gene-silencing approach to knockdown the RAD21 gene in MDA-MB-231 breast cancer cell line." (PMID 21255398, 2011). "RAD21 is believed to function in sister chromatid alignment as part of the cohesin complex and also in double-strand break repair and influences cellular proliferation, whereas EIF3S3 is reported to be amplified and overexpressed in up to 20% of breast carcinomas." (PMID 17133270, 2007). "In a gene expression profile of various breast cancer cell types, overexpression of both SMC1 and RAD21 was seen in MDA-MB-453, while not in MCF7 (an ER/PR positive breast cancer cell line)." (PMID 23717600, 2013).
Cornelia de Lange syndrome (41 papers, 2013 to 2026). "Cornelia de Lange Syndrome (CdLS) is a rare multisystem developmental disorder caused primarily by mutations in cohesin complex genes, including RAD21." (PMID 41226818, 2025). "Mutations in RAD21 result in Cornelia de Lange syndrome (OMIM 614701), a developmental disorder characterized by mild intellectual disability and several facial dysmorphisms." (PMID 33983923, 2021). "Cornelia de Lange syndrome (CdLS) is genetically heterogeneous; heterozygous variants in RAD21 cause the milder CdLS type 4 phenotype (OMIM #614701)." (PMID 41751561, 2026). "RAD21 encodes a key component of the cohesin complex, and variants in RAD21 have been associated with Cornelia de Lange Syndrome (CdLS)." (PMID 32193685, 2020). "In addition, heterozygous mutations in subunits of the cohesin complex (SMC1, SMC3, RAD21) or its chromatin loader (NIPBL) cause Cornelia de Lange syndrome (CdLS) which also frequently manifests as intellectual disability and neurodevelopmental delay." (PMID 39988079, 2025). "The most common cohesinopathy, Cornelia de Lange syndrome, is caused by dysfunction in a variety of cohesin subunits, such as NIPBL, SMC1A, SMC3, RAD21, BRD4, HDAC8, and ANKRD11." (PMID 40943870, 2025). "Our study provides the first molecular description of the co-occurrence of Cornelia de Lange syndrome (CdLS) and generalized pustular psoriasis (GPP), highlighting the potential mechanistic convergence of RAD21 and TNFAIP3 mutations." (PMID 41226818, 2025). "Surprisingly, DNA methylation analyses revealed a DNA methylation profile similar to the Cornelia de Lange syndromes 1–4 (CdLS) episignature, associated with variants in NIPBL, SMC1A, SMC3, and RAD21." (PMID 38273166, 2024). "HPE is also present in some patients with Cornelia de Lange syndrome associated with variants in SMC3, RAD21, and SCM1A." (PMID 35887945, 2022). "Genetic alterations of NIPBL, SMC1A, SMC3, HDAC8, and RAD21 genes are believed to trigger the development of Cornelia de Lange syndrome." (PMID 30606125, 2019). "Mutations in core cohesin subunits SMC1A, SMC3 and RAD21, or their regulators NIPBL and HDAC8, cause Cornelia de Lange syndrome (CdLS)." (PMID 26581180, 2015). "Mutations in RAD21, SMC1α and SMC3 have been shown to result in Cornelia de Lange syndrome, which causes intellectual disability and growth retardation and as well as facial and limb anomalies." (PMID 24992337, 2014). "Growth retardation, craniofacial anomalies, microbrachycephaly and reduced body fat have been described in cohesinopathies such as Cornelia de Lange syndrome CdLS, which is inherited in an autosomal dominant (NIPBL, SMC2 or RAD21) or X‐linked (SMC1A or HDAC8) pattern." (PMID 36627765, 2023). "Cornelia de Lange syndrome (CdLS), the best characterized cohesinopathy, is caused by mutations of cohesin regulators, such as NIPBL and HDAC8, or of cohesin subunits, including SMC1A, SMC3, and RAD21." (PMID 33262685, 2020). "Because WDSTS can phenotypic overlap with Pierpont syndrome, Cornelia De Lange syndrome and Kabuki syndrome, the candidate genes causing the later three syndromes (i.e. TBL1XR1, NIPBL, SMC1A, SMC3, RAD21, HDAC8, KMT2D, and KMD6A) in our cohort have been excluded." (PMID 30305169, 2018). "Pathogenic variants in NIPBL, MAU2, SMC1A, SMC3, RAD21, and HDAC8 cause Cornelia de Lange syndrome (CdLS), a multisystem disorder characterized by intellectual disability, facial dysmorphism, growth delay, and upper limb anomalies." (PMID 41492387, 2025). "Cornelia de Lange Syndrome (CdLS) is a genetically heterogeneous disorder predominantly caused by De Novo heterozygous pathogenic variants in NIPBL (80% of cases), with less frequent involvement of SMC1A (5%), HDAC8 (4%), SMC3 (1–2%), RAD21 (<1%), and BRD4 (<1%)." (PMID 40700109, 2025). "The most famous among them is the Cornelia de Lange Syndrome (CdLS), which is an autosomal dominant (NIPBL, SMC3, RAD21) and X-linked (SMC1 and HDAC8) disease with almost complete penetrance." (PMID 35222432, 2022).
Cornelia de Lange syndrome (continued). "Cornelia de Lange syndrome (CdLS) is the most prominent cohesinopathy and arises from heterozygous mutations, usually in the gene encoding cohesin regulator NIPBL, but sometimes in genes encoding the core mitotic-specific subunits of cohesin (RAD21, SMC3 and SMC1A) and the SMC3 deacetylase HDCA8." (PMID 34202641, 2021). "Cornelia de Lange syndrome (CdLS) results from autosomal dominant or X-linked mutations in NIPBL, SMC1A, SMC3, RAD21 or HDAC8." (PMID 31935221, 2020). "Cornelia de Lange syndrome (CdLS), a rare, multisystemic disorder, has been linked to genetic alterations in NIPBL, SMC1A, SMC3, HDAC8, and RAD21 genes." (PMID 30606125, 2019). "Genetic mutations in SMC1, SMC3, RAD21, and SCC3 have been implicated in neurodevelopmental disorders such as Cornelia de Lange syndrome (CdLS), but the subunit-specific contributions to gene regulation, particularly in the adult brain, remains unclear." (PMID 41013693, 2025). "Cornelia de Lange syndrome (CdLS, OMIM # 122470, #614701, #610759, #300590, and #300882) is a rare genetic disorder caused by variants in cohesion complex genes including NIPBL (NM_133433.3), SMC1A (NM_006304.4), SMC3 (NM_005445.3), HDAC8 (NM_018486.2), and RAD21 (NM_006265.3)." (PMID 35935361, 2022). "Variants in genes encoding various structural or functional components of the cohesin complex, including RAD21, SMC1A, SMC3, BRD4, STAG1/2, NIPBL, HDAC8, WAPL, ANKRD11 and in single individuals PDS5A and ESPL1, have been implicated in Cornelia de Lange Syndrome (CdLS)." (PMID 32193685, 2020). "However, after conducting whole exome sequencing analysis, no genetic variants associated with Cornelia de Lange syndrome, such as NIPBL, SMC1A, SMC3, RAD21 and HDAC8 were found." (PMID 38348454, 2024).
colorectal cancer (16 papers, 2017 to 2025). A primary or metastatic malignant neoplasm that affects the colon or rectum. "The 8q region also contains genes (RRM2B, NOV, RAD21) associated with the metastatic process, which is well described in studies on the progression of colorectal cancer." (PMID 40943426, 2025). "Besides, It has also been proven that the higher RAD21 expression in tumor tissues is associated with shorter DSS of patients with colorectal cancer." (PMID 36263204, 2022). "One of the most widely known perturbation studies in the 3D genomics field is the RAD21 depletion in HCT116 colorectal cancer cell line." (PMID 40950200, 2025). "RAD21 expression in colorectal cancer cells was modulated by Wnt/β-catenin activation and was associated with shorter disease-specific survival in patients with KRAS mutant tumors." (PMID 35860572, 2022). "Of note, Cohesin RAD21 haploinsufficiency regulates multiple initiating events in colorectal cancer and serves as a key transcriptional modulator for important genes in colorectal cancer." (PMID 35468892, 2022). "This system used a modified human colorectal carcinoma cell line HCT-116, with an AID domain tagging to both RAD21 alleles, an indispensable component of the cohesin complex." (PMID 32647330, 2020). "Similarly, elevated RAD21 expression in patients with colorectal cancer has been positively correlated with metastasis and shorter survival." (PMID 38378967, 2024). "Furthermore, transcription factors such as Heat Shock Transcription Factor 1(HSF1) and Double-Strand-Break Repair Protein Rad21 Homolog (RAD21) play a regulatory role with HNF4α in colorectal cancer metastasis." (PMID 36249028, 2022). "Cohesin RAD21 haploinsufficiency was found to affect a variety of tumor initiating events and was found to be a crucial transcriptional regulator of pivotal genes in colorectal cancer." (PMID 35468892, 2022). "Moreover, Xu et al7 showed that activation of the Wnt pathway promotes Rad21 gene expression, and elevated Rad21 expression tracks with reactivation of LINE‐1 expression in human sporadic colorectal cancer." (PMID 29797792, 2018). "Previously, it was reported that RAD21 overexpression is a marker for poor prognosis in breast, bladder, KRAS mutant colorectal carcinomas, and NSCLC." (PMID 35227290, 2022).